CCN4 (cellular communication network factor 4)
Description:
Downstream regulator in the Wnt/Frizzled-signaling pathway. Associated with cell survival. Up-regulates the anti-apoptotic Bcl-X(L) protein. Adheres to skin and melanoma fibroblasts. In vitro binding to skin fibroblasts occurs through the proteoglycans, decorin and biglycan.
Synonyms: WISP-1; WISP1; WISP1-OT1; WISP1-UT1; WISP1c; WISP1i; WISP1tc
Tractability: Antibody: UniProt places it where antibodies can reach, with medium confidence; UniProt predicts a signal peptide or a membrane-spanning region; its Gene Ontology location is reachable by antibodies, with medium confidence.
Gene: Protein-coding gene on chromosome 8 (133,191,039 to 133,231,690, forward strand). Ensembl gene ENSG00000104415.
Subcellular location: Secreted
Subcellular location (Human Protein Atlas): Cytosol; Predicted to be secreted
Gene Ontology:
Molecular function: protein binding; heparin binding; integrin binding
Biological process: positive regulation of inflammatory response; positive regulation of osteoblast differentiation; regulation of cytokine production; cell adhesion; cell-cell signaling; positive regulation of cell differentiation; positive regulation of smooth muscle cell migration; positive regulation of smooth muscle cell proliferation; signal transduction; bone development; glucose homeostasis; negative regulation of chondrocyte differentiation; negative regulation of fat cell differentiation; osteoblast differentiation; osteoclast differentiation; positive regulation of Wnt signaling pathway; positive regulation of wound healing; regulation of cell differentiation; regulation of multicellular organismal process
Cellular component: extracellular region; non-collagenous component of interstitial matrix; extracellular matrix; cytoplasm
Genetic constraint (gnomAD): Loss-of-function variants: 30 observed, 35.34 expected, observed/expected ratio (o/e) 0.85, 90% interval 0.63 to 1.15. The upper end of that interval is the gene's LOEUF score, 1.15, which puts it in group 5 of 6, group 1 being the genes least tolerant of losing a copy. Missense variants: 505 observed, 520.4 expected, observed/expected ratio (o/e) 0.97, 90% interval 0.9 to 1.04. Synonymous variants: 191 observed, 201.08 expected, observed/expected ratio (o/e) 0.95, 90% interval 0.84 to 1.07.
Homologues: Orthologues: chimpanzee CCN4 (99% identical), macaque CCN4 (96% identical), dog CCN4 (89% identical), pig CCN4 (88% identical), mouse Ccn4 (84% identical), guinea pig CCN4 (81% identical), rabbit CCN4 (81% identical), tropical clawed frog ccn4 (62% identical), rat Ccn4 (58% identical), zebrafish ccn4b (57% identical), zebrafish ccn4a (55% identical). Paralogues in human: CCN6 (40% identical), CCN2 (40% identical), CCN1 (37% identical), CCN3 (35% identical), CCN5 (26% identical).
Diseases named in the same sentence as CCN4 in open-access papers:
CCN4 is named in the same sentence as 137 diseases in open-access papers, as found by Europe PMC text mining. Sharing a sentence is not in itself a finding about the gene and the disease. The quoted sentences say what the papers report.
breast carcinoma (39 papers, 2003 to 2026). "CCN4 is involved in regulating cell differentiation, migration, proliferation, and cell adhesion and has been associated with breast cancer, colon cancer, larynx cancer, and malignant melanoma." (PMID 37452162, 2023). "CCN4–6 levels are also of significant prognostic value in breast cancers, and reduced CCN6 expression is strongly associated with a poor prognosis in 80% of aggressive inflammatory breast cancers." (PMID 18789696, 2008). "Overall, the changes observed between WT and CCN4 KO variants of the B16F0 and YUMM1.7 mouse models were consistent with the causal networks inferred from the breast cancer and melanoma datasets." (PMID 35418177, 2022). "The third prediction tested was related to CCN4 expression either promoting resting NK cells in the primary melanoma DAG or inhibiting active NK cells in the breast cancer DAG." (PMID 35418177, 2022). "In addition, the DAGs inferred from both the breast cancer and melanoma datasets suggest that a decrease in CD8+ T cells is driven indirectly through CCN4 expression via modulating cancer-associated fibroblasts or the activity of NK cells." (PMID 35418177, 2022). "The pro-tumorigenic CCN1, CCN2, CCN3, and CCN4 may lead to human breast cancer, although the anti-tumorigenic actions of CCN5 and CCN6 are also present." (PMID 34940056, 2021). "CCN1, CCN2, CCN3, and CCN4 are pro-tumorigenic and may be responsible for human breast carcinoma; while CCN1, CCN3, CCN5 and CCN6 have anti-tumorigenic effects." (PMID 34940056, 2021). "While the expression of CCN proteins varies in different cancer types, CCN1, CCN2, CCN3 and CCN4 participate in tumor development and act as oncogenes, but CCN1, CCN3, CCN5, and CCN6 inhibit tumor growth and play tumor-suppressive roles in breast carcinomas." (PMID 34940056, 2021). "Limited evidence indicates that CCN4, commonly known as WISP-1, has pro-tumorigenic features and functionality in breast cancer." (PMID 34940056, 2021). "CCN1, CCN2 and CCN4 are expressed at elevated levels in advanced breast cancers; increased CCN1 levels are thought to lead to more invasive breast cancers." (PMID 18789696, 2008).
lung fibrosis (27 papers, 2011 to 2025). "Other research groups showed that CCN4 mediates pulmonary fibrosis in mice and is upregulated in humans with idiopathic pulmonary fibrosis." (PMID 33946738, 2021). "In addition CCN-4, also known as WISP-1, has been shown to be necessary in the development of alveolar epithelial cell hyperplasia and epithelial-to-mesenchymal transition (EMT) leading to pulmonary fibrosis." (PMID 27446973, 2016).
melanoma (22 papers, 2003 to 2024). A malignant, usually aggressive tumor composed of atypical, neoplastic melanocytes. "Cell Communication Network Factor 4 (CCN4) is a secretory stromal cell protein generated by activation of the Wnt/β-catenin pathway that promotes the metastatic spread of melanoma by participating in the epithelial-mesenchymal transition." (PMID 38609997, 2024). "Functionally, expression of CCN4 promotes metastasis in melanoma by promoting a process similar to the epithelial-mesenchymal transition." (PMID 35418177, 2022). "In addition, when CCN4-knockout melanoma cells were implanted into immunocompetent mice, the infiltration of PMN-MDSCs was reduced." (PMID 38609997, 2024). "Similarly, the prevalence of macrophages was influenced by both CCN4 expression and oncogenic transformation in both melanoma datasets." (PMID 35418177, 2022). "Neutrophils were predicted to be independent of CCN4 expression in the melanoma datasets, which is not surprising considering that the majority of tumors had zero values for the Neutrophil feature." (PMID 35418177, 2022).
prostate carcinoma (20 papers, 2013 to 2026). A carcinoma that arises from epithelial cells of the prostate gland. "Osteoblast-secreted CCN4 participates in prostate cancer bone metastasis through the VCAM-1/integrin α4β1 system." (PMID 38994113, 2024). "CCN4 promotes adhesion of prostate cancer cells to bone via upregulation of VCAM1 and integrin α4β1 expression on osteoblasts and migration of prostate cancer cells themselves." (PMID 34228239, 2021). "CCN2, as observed in breast cancer, CCN3 and CCN4 levels are up regulated in prostate cancer and bone-metastatic cells or corresponding bone metastasis." (PMID 34228239, 2021). "An increased expression level of CCN4 has been found in prostate cancer tissue in the early stages, sera of patients, and carcinoma tissues of the mouse prostate cancer model TRAMP, which spontaneously develops to prostate carcinomas." (PMID 24551846, 2014). "Here we show that WISP1/CCN4 expression in prostate cancer tissues was up-regulated in early stages of the disease and, further, that it correlated with increased circulating levels of WISP1 in the sera of patients at early stages of the disease." (PMID 23977121, 2013). "Most importantly, the survival rate for patients with a high level of CCN4 transcripts was markedly lower than that for patients with a low level of CCN4 transcripts (P = 1.2 × 10−8) among solid tumors (breast, lung, and prostate cancer patients) that preferentially metastasize to the brain." (PMID 34031366, 2021). "CCN4 has been shown to play similar roles to CCN3 in prostate cancer." (PMID 24551846, 2014).
Obesity (13 papers, 2016 to 2025). Accumulation of substantial excess body fat. "Our results suggest a potential contribution of CCN4 in the pathogenesis of obesity-associated liver fibrosis." (PMID 33946738, 2021). "Taken together, our results suggest a contribution of CCN4 to the pathogenesis of obesity-associated liver fibrosis." (PMID 33946738, 2021). "In particular, in vivo experiments using an animal model of obesity-associated fibrosis in both CCN4-deficient and wild-type mice would shed light on underlying mechanisms." (PMID 33946738, 2021). "Our results suggest a potential contribution of CCN4 to the early pathogenesis of obesity-associated liver fibrosis." (PMID 33946738, 2021). "Because CCN4 can be secreted in the circulation and was recently described to play a role in the pathogenesis of obesity, we further investigated the association of its circulating levels with anthropometric and biochemical parameters as well as markers of hepatic function." (PMID 33946738, 2021). "However, it is unknown whether CCN4 contributes to the early stages of the development of human liver fibrosis associated with obesity and NAFLD." (PMID 33946738, 2021). "CCN4/WISP-1 and CCN5/WISP-2 have roles in metabolic disorders involving glucose homeostasis, such as insulin resistance, diabetes, and obesity, and have been associated with the development and regulation of different types of cancers." (PMID 34063397, 2021). "The aim of the present study was to investigate the role of CCN4 in liver fibrosis in severe obesity." (PMID 33946738, 2021). "In this study, RNA-seq, Western blot, and RT-PCR consistently confirmed that obesity induced by a high-fat diet significantly inhibited the Wnt/β-catenin signaling pathway in the tibia of mice, which was manifested by the downregulation of β-catenin and Ccn4." (PMID 41278194, 2025). "Thirdly, the study provided only cross-sectional observations giving no possibility to follow up on the CCN4 effects during the progression of obesity or weight loss." (PMID 33946738, 2021). "Our study provided the first piece of evidence that the novel adipokine WISP1/CCN4, which is increased in visceral obesity, might contribute to the early development of obesity-associated fibrosis even before marked cirrhotic changes occur." (PMID 33946738, 2021).
Insulin resistance (11 papers, 2020 to 2024). Increased resistance towards insulin, that is, diminished effectiveness of insulin in reducing blood glucose levels. "Wnt1 inducible signaling pathway protein 1 (WISP1/CCN4), a novel adipokine associated with visceral obesity and insulin resistance, also contributes to lung and kidney fibrosis." (PMID 33946738, 2021). "We recently characterized CCN4 as a novel adipokine associated with visceral obesity and insulin resistance." (PMID 33946738, 2021). "CCN4 can also activate the TLR4/JNK signaling pathway, linking CCN4-induced insulin resistance with inflammation." (PMID 33946738, 2021). "Further, circulating CCN4 levels are higher in patients with gestational diabetes and obese subjects with insulin resistance." (PMID 33946738, 2021). "In vitro experiments showed that CCN4 could inhibit insulin action in hepatocytes and muscle cells by affecting Akt/FOXO signaling and suggested that CCN4 might induce insulin resistance in the liver and muscle." (PMID 33946738, 2021).
liver fibrosis (11 papers, 2016 to 2026). "Nevertheless, in the whole cohort, we were able to find a range of significant associations of CCN4 with fibrosis markers and with the BMI suggesting the CCN4 role in liver fibrosis." (PMID 33946738, 2021). "WISP1/CCN4 is profibrotic and activates HSC in metabolic dysfunction-associated steatohepatitis and carbon tetrachloride-induced liver fibrosis." (PMID 40350059, 2026). "Our data also demonstrated an important role of HSC in the CCN4-mediated regulation of liver fibrosis." (PMID 33946738, 2021). "However, the molecular mechanisms of the relationship between CCN4 and liver fibrosis have to be evaluated in future studies." (PMID 33946738, 2021). "However, the exact molecular mechanism of the observed CCN4 effects in liver fibrosis still needs to be elucidated." (PMID 33946738, 2021). "Thus, our findings on stellate cells highlighted a role for CCN4 in the induction of liver fibrosis." (PMID 33946738, 2021). "To investigate whether HSC activation represents a link between CCN4 and liver fibrosis, we investigated the effects of CCN4 on LX-2 cells, a well-established model for the study of HSC." (PMID 33946738, 2021). "Similarly, CCN4/WISP1 is profibrotic, since blockade of this molecule decreases experimental liver fibrosis in vivo." (PMID 27829832, 2016). "Particularly, an involvement of CCN4 was demonstrated in mouse lung and kidney fibrosis development as well as CCL4-induced liver fibrosis, increasing the synthesis of extracellular matrix components (ECM) in fibroblasts." (PMID 33946738, 2021). "Based on our findings, we suggest that CCN4 might accelerate both HSC activation and liver inflammation contributing, in this way, to the aggravation of liver fibrosis." (PMID 33946738, 2021). "Finally, CCN4 upregulated its own expression in HSC in combination with TGF-β, which might accelerate the progression of liver fibrosis via a vicious circle." (PMID 33946738, 2021). "Thus, our data suggest that CCN4 might stimulate both excessive hepatic production of ECM proteins, such as collagens and αSMA and increased expression of ECM turnover enzymes, which are both increased in the pathogenesis of liver fibrosis." (PMID 33946738, 2021).
osteoarthritis (11 papers, 2013 to 2024). A noninflammatory degenerative joint disease occurring chiefly in older persons, characterized by degeneration of the articular cartilage, hypertrophy of bone at the margins and changes in the synovial membrane. "In particular, CCN1 showed proangiogenic activities in HUVEC cells through binding to αvβ3- and α6β1-integrins, while WISP1 (CCN4) induced IL-6 expression in fibroblasts from synovial membrane from patients with osteoarthritis (OASMFs) through αvβ5-integrin." (PMID 38145300, 2024). "Substantial evidence implicates four of the proteins (CCN1, CCN2, CCN3 and CCN4) in the inflammatory pathologies of rheumatoid arthritis (RA) and osteoarthritis (OA)." (PMID 33919365, 2021). "Osteoarthritis synovial fibroblasts (OASFs) showed significant expression of CCN4 and the expression was higher than in normal SFs." (PMID 23343403, 2013). "CCN4 is related to up-regulation in the cartilage of patients with osteoarthritis." (PMID 23343403, 2013). "Similarly in a mouse model of osteoarthritis, stimulation of macrophages with CCN4 resulted in production of MMPs 3, 9 and 13; while in mucosal epithelial cells macrophages released IL-10, which increased CCN4 via CREB activation and resulted in wound repair." (PMID 34080128, 2021). "One exciting therapeutic target for osteoarthritis that is emerging as a novel consideration is Wnt1 inducible signaling pathway protein 1 (WISP1), also known as CCN4." (PMID 26893943, 2016). "CCN1, CCN2, CCN4, and CCN5 have been found to be expressed to a greater extent in knee cartilage during osteoarthritis and rheumatoid arthritis when compared to normal controls." (PMID 26893943, 2016). "However, the role of CCN4 in IL-6 production in osteoarthritis synovial fibroblasts (OASFs) has not been extensively studied." (PMID 23343403, 2013).
renal fibrosis (11 papers, 2016 to 2024). A final common manifestation of a wide variety of chronic kidney diseases characterized by glomerulosclerosis and tubulointerstitial fibrosis. "CCN4 was also shown to be associated with renal fibrosis in a TGF-β-induced tubular epithelial cell model, a mouse model of obstructive nephropathy, and in subjects with chronic kidney disease." (PMID 33946738, 2021).
osteosarcoma (10 papers, 2013 to 2026). A usually aggressive malignant bone-forming mesenchymal neoplasm, predominantly affecting adolescents and young adults. "CCN4 also promotes migration, invasiveness and metastasis of osteosarcoma cells upregulating MMP-2 and MMP-9 expression." (PMID 34228239, 2021). "CCN1, CCN2, CCN3 and CCN4 are all poorly expressed in healthy adult bony tissues, but they are up regulated in primary samples as well as osteosarcoma cell lines." (PMID 34228239, 2021). "In our previous work, we show that the expression of CCN4 in osteosarcoma patients was significantly higher than that in normal bone and corrected with tumor stage." (PMID 24551846, 2014). "CCN4 also showed similar correlation like CCN1 and CCN3 in osteosarcoma." (PMID 24551846, 2014). "WISP-1, also known as CCN4, contributes to tumorigenesis, is a predictor of poor survival and is expressed at high levels not only in OSCC, but also in several other types of cancer, including esophageal cancer, pancreatic ductal adenocarcinoma, and osteosarcoma." (PMID 31795469, 2019).
glioma (9 papers, 2014 to 2025). A benign or malignant brain and spinal cord tumor that arises from glial cells (astrocytes, oligodendrocytes, ependymal cells). "It has been shown that CCN1, CCN2, and CCN4 all contribute to glioma progression, in agreement with our findings." (PMID 36589241, 2022). "In the validation cohort of glioma patients, we found that CCN4, LGR6, MMP7 and TCF7 were obviously upregulated." (PMID 34852024, 2021). "This indicated that CCN4 was closely related to IDHwt and TERT promoter, which affected the prognosis of glioma." (PMID 36589241, 2022). "The elevated expression of WISP1 (CCN4) and PDGFA proteins in the invasive glioma cells was confirmed." (PMID 25365423, 2014). "Our data indicated that the Wnt pathway activation related genes such as CCN4, FOSL1, LGR6, MMP7, RAC2, SERPINF1 and TCF7 were upregulated, while Wnt pathway inactivation related gene such as CXXC4 was downregulated in radiotherapy treated glioma patients from TCGA database." (PMID 34852024, 2021).
gastric cancer (8 papers, 2007 to 2024). A primary or metastatic malignant neoplasm involving the stomach. "Differential expression analysis showed that IGFBP7, CCN2, ESM1, CCN4 and CCN6 mRNA were over-expressed in gastric cancer tissues while CCN5 mRNA was down-expressed (all p < 0.05)." (PMID 37304887, 2023). "From overall survival analysis, gastric cancer patients with high expression of IGFBP7, CCN2, CCN3, CCN1, CCN5 or CCN4 would have a poor survival time (all p < 0.05)." (PMID 37304887, 2023).